ADAMTS18 (ADAM metallopeptidase with thrombospondin type 1 motif 18)
Diseases named in the same sentence as ADAMTS18 in open-access papers (continued):
Sharing a sentence is not in itself a finding about the gene and the disease.
tumor (continued). "Analysis of epigenetic mechanisms of transcriptional control then showed that ADAMTS18 is regulated via methylation of CpG islands in its promoter and that it is a tumor-specific methylation." (PMID 24213506, 2012). "ADAMTS18 promoter methylation is also prevalent in a large number of tumor samples of gastric, colorectal and pancreatic origins." (PMID 24213506, 2012). "These tumor-bearing Her2t/w/Adamts18−/− mice also developed metastases in the liver (6 of 32, ~ 19%, P = 0.0219), kidney (5 of 32, ~ 16%, P = 0.0457), and peritoneal cavity (3 of 32, ~ 10%, P = 0.198) when compared with Her2t/w/Adamts18+/+ mice." (PMID 38287441, 2024). "ADAMTS18 fulfills multiple distinct roles in tumor tissues, affecting intracellular signals and tumor microenvironment, which is reflected in the complexity of biological functions and different expression patterns of ADAMTS18 in different types of tumor tissues." (PMID 38482210, 2024). "In addition, we will highlight the biological functions of ADAMTS18 in the tumor microenvironment, including the regulation of cell proliferation signals, death patterns, invasion, and migration, which influence cancer progression." (PMID 38482210, 2024). "Thus, disruption of ADAMTS18 signaling promotes intestinal inflammation in mice, which in part creates a tumor-promoting microenvironment for mice." (PMID 38482210, 2024). "However, new evidence suggests that the complexity of ADAMTS18’s mode of action in cancer has extended to fine-tuned factors in cell signaling pathways and tumor microenvironment." (PMID 38482210, 2024). "Indeed, ADAMTS7 was detected in the urine of bladder cancer patients; while reduced serum levels of ADAMTS18 correlated with high tumour stage, positive lymph node metastasis, distant metastasis and shorter overall survival in cervical cancer patients." (PMID 38948119, 2024). "ADAMTS18 was previously found to be downregulated in numerous carcinoma cell lines, which suggested that it could be a tumor suppressor." (PMID 35053843, 2022). "We further assessed tumor‐suppressive functions of ADAMTS18." (PMID 28503860, 2017). "Immunohistochemistry staining showed that the number of cells with nuclear β-catenin translocation was significantly increased in Adamts18 KO tumor cells compared to WT tumor cells [cells with nuclear β-catenin translocation (%), WT vs. KO, 13.1 ± 2.9 vs. 22.7 ± 4.3; P = 0.0004]." (PMID 28145888, 2017). "In addition, the results of in situ TUNEL assay showed Adamts18 KO tumor cells underwent less apoptosis than WT tumor cells [apoptotic index (%), WT vs. KO, 18.1 ± 4.7 vs. 10.7 ± 3.1; P = 0.0044]." (PMID 28145888, 2017). "Thus, ADAMTS18 as an antimetastatic tumor suppressor antagonizes AKT and NF‐κB signaling in breast tumorigenesis." (PMID 28503860, 2017). "In this study, we aimed to identify a novel extracellular proteinase ADAMTS-18 that could be a potential tumor suppressor gene." (PMID 26841794, 2016). "To assess whether the ADAMTS18 gene was down-regulated in ccRCC tumor tissues, we initially determined its expression in ccRCC-derived cell lines using RT-PCR." (PMID 25569086, 2015). "Additionally, the matched tumor samples for the 3 adjacent normal tissue samples with ADAMTS18 gene hypermethylation were also hypermethylated." (PMID 25569086, 2015). "More importantly, the paired tumor samples of these 3 adjacent normal tissues were also hypermethylated, indicating that ADAMTS18 gene analysis may be useful in diagnosing ccRCC." (PMID 25569086, 2015). "ADAMTS18 was identified as a novel tumor suppressor gene located at 16q23.1." (PMID 24213506, 2012). "Thus, it could be speculated that pro-tumor functions or anti-oncogenic properties elicited by the ADAMTS18 may depend on the substrates or interacting partners present in the cell microenvironment." (PMID 38482210, 2024). "Furthermore, the methylation frequency of ADAMTS18 varies in a variety of tumor tissues." (PMID 38482210, 2024).
tumor (continued). "Our results suggested that the four mRNA vaccine targets, namely, ADAMTS18, COL10A1, PPEF1, and STRA6, were positively correlated with the infiltration of dendritic cell, thereby activating cytotoxic T cells against tumor cells." (PMID 35874675, 2022). "The current study results revealed the upregulation of four genes including ADAMTS18, CDKN2B, and FHIT as tumor suppressors and WNT5B as an oncogene in the patients." (PMID 35176183, 2022). "Conversely, proteins of interest in tumor-bearing rats elevated following OKN-007 treatment included ABCA6, ADAMTS18, VWA8, MACF1, and LAMA5." (PMID 35053843, 2022). "Conversely, proteins of interest in tumor-bearing rats that were elevated following OKN-007 treatment included ABCA6, ADAMTS18, VWA8, MACF1, and LAMA5." (PMID 35053843, 2022). "In addition, the Chinese herbal compound SanHuang decoction and ADAMTS18 have a synergistic effect by increasing the proportion of CD8+ and CD4+T cells and reducing the ratio of CD45+/PD-L1 to increase tumor immune infiltration and inhibiting immune escape." (PMID 38482210, 2024). "Despite the recent breakthroughs in tumor biology of ADAMTS18, there is no literature systematically discussing the relationship between ADAMTS18 and cancer." (PMID 38482210, 2024). "ADAMTS18 and CHRDL1 are putative tumor suppressor genes and epigenetic silencing of these genes diagnosed with various cancer types, but inactivation of these genes might be linked with progression of pituitary prolactinoma." (PMID 33709028, 2021). "ADAMTS18 promoter methylation was detected in 70.8% of tumor tissues by methylation‐specific PCR, but none of the normal tissues." (PMID 28503860, 2017). "A number of fast evolving, placental genes show tumorigenic or tumor suppression activity (ADAM12, ADAMTS18, CAPN6, EGFL6, HTRA4, LIN28B) and others are involved in disorders associated with epithelial and connective tissues (FBN2) or have immune functions (IL1RL1, PRG2, SIGLEC6)." (PMID 26641094, 2015). "Another report also identified ADAMTS18 as a highly down-regulated gene in breast carcinoma as compared to normal tissue irrespective of tumor heterogeneity, type or grade." (PMID 24213506, 2012). "In comparison, high ADAMTS18 expression was retained in non-tumor cell lines and in immortalized but non-transformed epithelial cell lines, indicating that this gene is likely to be specifically down-regulated in carcinoma." (PMID 24213506, 2012). "From an oncological point of view, the relationship between the tumor-promoting and anti-tumorigenic properties of ADAMTS18 and specific substrates and interacting proteins has not been well explained, although the biological functions of ADAMTS18 have been extensively reported in the literature." (PMID 38482210, 2024). "In addition, mutant ADAMTS18 overexpression confers a higher proliferation rate to tumor cells in vitro under low serum conditions although no growth advantages were observed under normal serum conditions." (PMID 24213506, 2012).
cancer (13 papers, 2012 to 2024). A tumor composed of atypical neoplastic, often pleomorphic cells that invade other tissues. "ADAMTS18 is located at 16q23.1 in the human genome, and heterozygous deletions in the 16q23 region have been strongly associated with a variety of cancers." (PMID 38482210, 2024). "Data from Gene Expression Profiling Interactive Analysis (GEPIA) suggest that ADAMTS18 is associated with cancer because of their altered expression in different tumors." (PMID 38482210, 2024). "Although ADAMTS18 was initially associated with cancer and thrombosis, recently ADMATS18 deficiency in zebrafish or in mice were associated with observations of defective angiogenesis and vascular malformations, respectively." (PMID 34320216, 2021). "Increasing evidence suggests that hypermethylation of the ADAMTS18 promoter CpG Islands (CGI) leads to epigenetic inactivation in a variety of cancers, thus making ADAMTS18 a tumor suppressor gene (TSG)." (PMID 38482210, 2024). "Initially, the link between ADAMTS18 and cancer was based on the altered mode of action of ADAMTS18 in different types of cancer." (PMID 38482210, 2024). "Curcumin down-regulates the NF-κB and AKT signaling pathways, reverses the methylation of ADAMTS18 in ccRCC, and inhibits the growth of cancer cells by up-regulating ADAMTS18 expression." (PMID 38482210, 2024). "In this review, we will summarize the expression pattern and prognostic value of ADAMTS18 in various cancers." (PMID 38482210, 2024). "So far, there is a gap in this research although ADAMTS18 in combination with some drugs has shown therapeutic effects in the field of anti-cancer." (PMID 38482210, 2024). "Since ADAMTS18 has the potential to be a prognostic indicator for a variety of cancers, it is of great significance to study ADAMTS18 as an anticancer-targeted drug." (PMID 38482210, 2024). "In the large number of primary cancer samples, ADAMTS18 downregulation was found to be the result of promoter methylation, and gene methylation is an ideal biomarker for early diagnosis or efficacy monitoring." (PMID 38482210, 2024). "Since these changes occur in the early stages of cancer, it has been hypothesized that ADAMTS18 can aid in early cancer diagnosis and prognosis." (PMID 38482210, 2024). "ADAMTS18 has been widely documented to play a role as a TSG in most types of cancer." (PMID 38482210, 2024). "ADAMTS18 dysregulation plays an important role in many disease processes including cancer." (PMID 28503860, 2017). "In conclusion, ADAMTS18 may be a good prognostic factor for many cancer types." (PMID 38482210, 2024). "Thus, the roles of ADAMTS18 in different human cancers require further clarification." (PMID 24213506, 2012). "The largest FMGS identified in all these cancer stages contained 8 genes (k = 8; RP1, PCDHAC2, TENM3, SPHKAP, ODZ3, ADAMTS18, SCN5A, PKHD1L1) found in SKCM-stage IV." (PMID 27556693, 2016). "ADAMTS18 is a part of the ADAMTS (A Disintegrin and Metalloproteinase with Thrombospondin motifs) family proteins, which take part in vital roles in cancer progression and metastasis in various cancers." (PMID 35053843, 2022). "Surprisingly, no obvious deletion was detected in cancers with reduced ADAMTS18 expression." (PMID 24213506, 2012). "Therefore, more studies on the molecular mechanisms by which ADAMTS18 regulates cancer are needed in the future, which will not only contribute to the understanding of the physiological mechanisms of ADAMTS family members but also to the development of less toxic cancer therapies." (PMID 38482210, 2024).
infection (2 papers, 2016 to 2021). The state of being infected such as from the introduction of a foreign agent such as serum, vaccine, antigenic substance or organism. "In contrast, ADAMTS18, CLN8, RDH10 and TNPO1 were shown to be up-regulated following infection in HSaVEC, indicating that gene regulation differs for these genes between the endothelial cells." (PMID 26837541, 2016).
ADAMTS18 also shares sentences with these, for which no sentence is quoted: ectopia lentis (3 papers); telecanthus (3); colon cancer (2); esophageal cancer (2); nasopharyngeal carcinoma (2); autism (1); cataract (1); cerebral malaria (1); childhood glaucoma (1); Chorioretinal atrophy (1); cone-rod dystrophy (1); dementia (1); esophageal squamous cell carcinoma (1); hyperopia (1); immune disorders (1); myoepithelioma (1); Neurodevelopmental delay (1); night blindness (1); occipital encephalocele (1); osteosarcoma (1); renal hypoplasia (1); retinal detachment (1); rhegmatogenous retinal detachment (1); vitreoretinal degeneration (1).